CCDC120 (coiled-coil domain containing 120)
Description:
Centriolar protein required for centriole subdistal appendage assembly and microtubule anchoring in interphase cells. Together with CCDC68, cooperate with subdistal appendage components ODF2, NIN and CEP170 for hierarchical subdistal appendage assembly. Recruits NIN and CEP170 to centrosomes. Also required for neurite growth. Localizes CYTH2 to vesicles to allow its transport along neurites, and subsequent ARF6 activation and neurite growth.
Synonyms: JM11
Tractability: PROTAC: UniProt records ubiquitination sites on it; its protein half-life has been measured.
Gene: Protein-coding gene on chromosome X (49,053,572 to 49,069,857, forward strand). Ensembl gene ENSG00000147144.
Subcellular location: Cytoplasm, cytoskeleton, microtubule organizing center, centrosome, centriole; Cytoplasm; Cell projection, neuron projection; Cell projection, growth cone; Endosome
Subcellular location (Human Protein Atlas): Mitochondria
Gene Ontology:
Molecular function: protein binding
Biological process: intracellular protein localization; microtubule anchoring at centrosome
Cellular component: centriolar subdistal appendage; centriole; cytoplasm; endosome; growth cone; neuron projection
Homologues: Orthologues: chimpanzee CCDC120 (95% identical), macaque CCDC120 (94% identical), pig CCDC120 (92% identical), dog CCDC120 (89% identical), guinea pig CCDC120 (88% identical), rat Ccdc120 (85% identical), mouse Ccdc120 (81% identical), rabbit CCDC120 (75% identical), tropical clawed frog CCDC120 (36% identical), zebrafish ccdc120b (28% identical), zebrafish ccdc120a (27% identical). Paralogues in human: INAVA (19% identical).
Diseases named in the same sentence as CCDC120 in open-access papers:
CCDC120 is named in the same sentence as 5 diseases in open-access papers, as found by Europe PMC text mining. Sharing a sentence is not in itself a finding about the gene and the disease. The quoted sentences say what the papers report.
cancer (1 paper, 2018). A tumor composed of atypical neoplastic, often pleomorphic cells that invade other tissues. "The two mechanisms defined are intrinsically related to the pathogenesis of IBD, and likely will apply as general rules for the CUPID domains of FRMD4A, FRMD4B, and CCDC120 - proteins implicated in neurite outgrowth, and in human cancer, Alzheimer’s, celiac, and heart disease." (PMID 30355448, 2018).
CCDC120 also shares sentences with these, for which no sentence is quoted: breast carcinoma (1 paper); breast tumors (1); heart disease (1); ovarian carcinoma (1).